LEP (leptin)
Diseases named in the same sentence as LEP in open-access papers (continued):
Sharing a sentence is not in itself a finding about the gene and the disease.
hypertriglyceridemia (continued). "Among patients with PL, 61% were responders regarding glucose homeostasis, and 61% were responders regarding hypertriglyceridemia at year 1, with those with more severe metabolic disease and lower leptin at baseline, as well as those with preserved β-cell functions, likely being better responders." (PMID 38952397, 2024). "The diurnal leptin amplitude and lower evening meal hypertriglyceridemia." (PMID 34369385, 2021). "The latest studies in leptin suggest that an analog of leptin may treat DM and hypertriglyceridemia." (PMID 35027962, 2021). "Next, we addressed whether leptin gene methylation is truly altered in the offspring of women with gestational hypertriglyceridemia." (PMID 33431976, 2021). "The role leptin on ANGPTL3 expression and plasma level in humans was recently documented in a study conducted in patients with generalized lipodystrophy, a leptin deficient condition associated with hypertriglyceridemia." (PMID 29752428, 2019). "Clinical and laboratorial characteristics of obese children with or without hypertriglyceridemia and controls showed that obese children with hypertriglyceridemia have lower adiponectin and higher leptin-to-adiponectin ratio when compared to the controls and children without hypertriglyceridemia." (PMID 29895283, 2018). "Hypertriglyceridemia may also be another contributor to leptin resistance, as high triglyceride levels decrease leptin transport across the BBB." (PMID 26881138, 2016). "In addition, the circulating concentrations of three hormones that regulate metabolism, resistin, leptin, and glucose-dependent insulinotropic polypeptide, were reduced by TIMEx consumption, which may be involved in its effect to prevent hypertriglyceridemia." (PMID 35208189, 2022). "Interestingly, we found that RSV alleviates some MeS traits induced by HFD by reducing triglycerides and leptin plasma levels in all HFD+RSV groups compared to the HFD group, suggesting that RSV can promote peripheral effects regarding hypertriglyceridemia and leptin resistance induced by HFD." (PMID 33535619, 2021). "In this study, female HHTg rats exhibited more pronounced hypertriglyceridemia and a procoagulant state, whereas male rats showed higher non-fasting blood glucose levels and serum leptin levels." (PMID 41246008, 2025). "Obese children with/without hypertriglyceridemia showed an increase of leptin and leptin-to-adiponectin ratio, and a decrease in adiponectin." (PMID 29895283, 2018). "In addition, gender differences were observed; men who were ever tobacco users, as well as those with hypertriglyceridemia and high LDL-C had significantly higher leptin levels." (PMID 22533665, 2012). "The accumulation of body fat as well as the onset of insulin intolerance, liver steatosis, and hypertriglyceridemia as well as leptin levels could be restored in partially but not completely leptin-deficient mice." (PMID 39683624, 2024). "In conclusion, we show that leptin signaling in the brain protects from ectopic lipid accumulation in the liver by stimulating TG secretion and reducing lipid production without inducing hypertriglyceridemia." (PMID 31222048, 2019). "Here we demonstrate that brain leptin signaling increases TG export and decreases de novo lipogenesis in the rat liver, which within weeks reduces hepatic lipid content independently of changes in body weight and food intake, and without any accompanying hypertriglyceridemia." (PMID 31222048, 2019).
Stroke (83 papers, 2007 to 2026). Sudden impairment of blood flow to a part of the brain due to occlusion or rupture of an artery to the brain. "Elevated leptin levels have been associated with higher stroke risk, while reduced adiponectin levels are linked to vascular dysfunction and microvascular damage." (PMID 40013043, 2025). "A few clinical studies presented circumstantial association between hyperleptinemia and stroke, supposedly through leptin-induced NF-kB activation and consequent local inflammatory response." (PMID 35015765, 2022). "Leptin was also associated with cardiovascular risk factors such as insulin resistance, obesity, hypertension, and increased incidence of stroke." (PMID 35015765, 2022). "Serum leptin is associated with first-ever acute IS, lesion size, and stroke severity in a Chinese cohort." (PMID 34685473, 2021). "Another prospective study on patients with a history of stroke showed that higher leptin values were associated with higher stroke incidence." (PMID 34445740, 2021). "Other cardiovascular diseases where high serum leptin level is reported to be associated with risk are stroke, left cardiac hypertrophy and chronic heart failure." (PMID 33489600, 2020). "Sociodemographic-adjusted studies indicated that high leptin was associated with an increased risk of CHD instead of stroke." (PMID 28278178, 2017). "In a large population-based study, LEP levels were higher in women than men, showing an increased risk of nearly twofold for stroke in women when compared to men." (PMID 26783391, 2015). "Leptin reduces neuronal apoptosis, increases cell survival and proliferation, and reduces damage caused by stroke; specifically in the hippocampus, leptin facilitates plasticity." (PMID 26260473, 2015). "In our assessment LEP was also reported to be a stroke risk factor for both men and women, with levels found to be three times higher in women than in men with ischemic stroke, but still higher than in controls." (PMID 26783391, 2015). "There are a lot of reports about the association of leptin and adiponectin with stroke, and leptin and adiponectin show differential association patterns with ischemic stroke." (PMID 23431245, 2013). "Low leptin levels were associated with worse outcomes and greater severity of stroke." (PMID 39201031, 2024). "Although resistin and leptin have been studied in relation to the risk of stroke and mortality in patients with AIS, our study is, to the best of our knowledge, the first to incorporate resistin into a validated predictive score for three-year mortality in AIS patients." (PMID 39336454, 2024). "Moreover, plasma leptin levels >14.1 ng/mL were independently associated with a significant increase in risk of MACE, while leptin levels > 9.9 ng/mL predicted a higher risk of ACS or stroke." (PMID 36676179, 2023). "In addition to this, an increased leptin/adiponectin ratio at admission is associated with good outcomes in atherothrombotic stroke patients." (PMID 34445740, 2021). "Moreover, in a meta-analysis of prior studies between leptin and stroke, the combined risk ratio across all studies was 1.09 (95% CI, 0.87–1.37) in the adjusted analyses." (PMID 28278178, 2017). "Six studies provided sociodemographic-adjusted data on the risk of stroke and leptin." (PMID 28278178, 2017). "However, in a 4-year follow-up of the Jackson Heart Study with 5170 participants, there is a significant association between leptin and stroke in women." (PMID 28278178, 2017). "This study documented that leptin could be a potential biomarker for risk stratification of cardioembolic stroke in MetS patients and that the heterogeneity of stroke subtypes should be considered for more refined and precise clinical stroke studies." (PMID 29225622, 2017).
Stroke (continued). "High leptin levels have been significantly associated with the incidence of ischemic stroke in both men and women, independent of other cardiovascular risk factors, but its prognostic role in the outcomes after stroke remains uncertain, as studies have shown both a protective and harmful role." (PMID 39336454, 2024). "This pilot study revealed that leptin could be a potential biomarker for risk stratification of cardioembolic stroke in MetS patients and that heterogeneity of stroke subtypes should be considered for more refined and precise clinical stroke studies." (PMID 29225622, 2017). "Next, we observed that the intravenous delivery of leptin-PEG-FBP localized to Fas-expressing brain regions in photothrombotic stroke mouse models of brain ischemia." (PMID 38203830, 2024). "In patients with end-stage kidney disease, higher leptin values were recorded in those with a history of stroke." (PMID 39062887, 2024). "Still, among patients with stroke, serum leptin values were lower in those who also had congestive heart failure." (PMID 39062887, 2024). "Instead, elevated leptin values ​​are correlated with the development of post-stroke depression and poor functional and cognitive outcomes." (PMID 36745280, 2023). "Leptin administered after stroke in mouse models improves outcomes, neuronogenesis and angiogenesis of the perilesional brain tissue." (PMID 36745280, 2023). "Higher leptin/adiponectin ratio are correlated with better neurological outcomes in patients with stroke." (PMID 36745280, 2023). "Low leptin levels upon admission for stroke were negatively correlated with 3-months poor outcome and mortality in patients with type 2 diabetes." (PMID 36745280, 2023). "Based on these data, several studies have been conducted on mouse models to clarify the role of leptin in the pathogenesis of stroke, and on neuromotor or behavioral outcomes and mortality." (PMID 36745280, 2023). "Leptin levels peaked modestly on day three after the stroke, which is in line with previous studies that found increased leptin levels in etiological subgroups of stroke patients." (PMID 37587512, 2023). "Increasing evidence suggests that leptin potentiates angiogenesis and plays a beneficial role in stroke." (PMID 36078162, 2022). "High level of leptin, positively correlates with risk of CV events like coronary heart disease (CHD), stroke or coronary events." (PMID 35488267, 2022). "In stroke patients, both ischemic and hemorrhagic types, the value of leptin was significantly higher compared to healthy subjects." (PMID 34445740, 2021). "As a result, altered SP1 transcriptional activity leads to promoted production of leptin, which ameliorates neurological deficits and reduces infarct volumes after stroke." (PMID 33092540, 2020). "Adipose tissue secretes many types of adipokines (such as leptin, interleukin 6, and adiponectin) that play a role in the progression of stroke." (PMID 30038059, 2018). "Leptin has also been shown to be neuroprotective and induces neurogenesis and angiogenesis after stroke." (PMID 28533765, 2017). "Previous research suggests that elevated leptin levels are involved in cardio-cerebrovascular disorders such as myocardial infarction and stroke." (PMID 27598978, 2017). "A published meta-analysis, comprising eight nested case-control studies with a total of 1980 CVD patients and 11567 participants, indicated a significant association between leptin and pathogenetic risk of CHD and stroke." (PMID 28278178, 2017). "After careful screening and independent selection, thirteen eligible studies met all the inclusion criteria, including five studies exploring the association between leptin and risk of CHD, four studies for stroke and four studies for both." (PMID 28278178, 2017). "More specifically, we studied the associations of adiponectin, leptin, and the interleukin-6 product CRP (used as a proxy for interleukin-6) with incident CHD and stroke in the Inter99 study." (PMID 26035431, 2015).
Stroke (continued). "Firstly, leptin induces neurogenesis and angiogenesis after stroke and leads to increased leptin receptor and pAMPK concentrations." (PMID 25061971, 2014). "In a different direction, leptin appears more as a reasonable predictor of stroke, especially hemorrhagic stroke, based on the majority of the available evidence." (PMID 24350185, 2013). "Leptin, an adipose derived hormone, has been found to confer neuroprotection following experimental stroke." (PMID 23510433, 2013). "This increase in leptin expression possibly contributed to the lower incidence of stroke in the candesartan-treated group." (PMID 23876211, 2013). "It is reported that higher leptin levels and lower adiponectin levels were found in stroke patients." (PMID 23431245, 2013). "Neuroprotective roles for leptin have also been found in animal models of stroke where leptin administration protects against both oxygen-glucose deprivation and middle cerebral artery occlusion." (PMID 22013440, 2011). "Our results contribute to the body of contradictory literature on the subject of leptin and stroke." (PMID 39201031, 2024). "However, given that there are reports suggesting that leptin itself can alleviate stroke, further studies must be conducted to gain a more comprehensive understanding of the role of leptin in ischemic strokes." (PMID 38203830, 2024). "In chronic heart disease (CHD) patients, elevated leptin levels were significantly associated with an increased risk of cardiac death, acute coronary syndrome, non-fatal MI, stroke, and hospitalization for congestive heart failure." (PMID 36901837, 2023). "Leptin has been related to neuroprotection after spinal cord injury or stroke." (PMID 36982140, 2023). "On the other hand, a recent Framingham study’s results showed that leptin levels were not directly related to the risk of all stroke incidents, including ICH." (PMID 36078162, 2022). "Thus, at first, we experimented the doses of leptin (1, 10, or 20 μg), which are often selected dosages in the study of stroke, and chose day 7 to evaluate the pro-angiogenesis properties of leptin." (PMID 36078162, 2022). "Since leptinR/Jak-STAT signaling pathway has been found to be related to the angiogenesis through leptin in stroke and tumors, we are interested in whether leptin promotes angiogenesis in the context of ICH through the activation of this pathway." (PMID 36078162, 2022). "Circulating biomarkers which constitute the typical lipid patient profile (LDL-C, TC, triglyceride, Ox-LDL, Lp-PLA2), inflammatory biomarkers such as hs-CRP, TNF-α, IL-6, adipokines (adiponectin, leptin, FABP4) and homocysteine are related to the high risk of future stroke." (PMID 34829489, 2021). "The design of this study does not allow an explanation for these gender differences, but may be due to sex-differences in leptin signalling and we have reported similar sex-related differences in leptins ability to predict stroke and diabetes." (PMID 28919840, 2017). "Meta-analysis using a random-effect model indicated that the risk of stroke did not increase in patients with high leptin (OR = 1.21, 95% CI 0.98–1.48; P for heterogeneity = 0.006, I2 = 63%)." (PMID 28278178, 2017). "However, the results of the research studying the association of leptin with CHD and stroke are inconsistent." (PMID 28278178, 2017). "Characteristics of included studies on leptin and risk of CHD and Stroke." (PMID 28278178, 2017). "Larger prospective studies, both in the general population and in the patients with a history of stroke, are needed to determine whether the measurement of leptin serum levels in case of MetS and FA presence could improve stroke prediction." (PMID 29225622, 2017). "In a subgroup meta-analysis, a high leptin level was not independently associated with stroke in females (OR = 1.13, 95% CI 0.87–1.47) or males (OR = 0.80, 95% CI 0.59–1.09)." (PMID 28278178, 2017).
Stroke (continued). "In this study, leptin levels were not directly related to the overall risk of stroke incidence but there was an inverse association with stroke in the top waist-hip ratio quartile." (PMID 29225622, 2017). "Leptin levels increased with increasing severity of stroke as defined by the NIHSS score." (PMID 25061971, 2014). "Thirdly, the serum level of leptin was tested only one time at admission, further studies are needed to assess how leptin levels change across time after stroke and whether levels drawn at later points provide improved prognostic information." (PMID 25061971, 2014). "It is not clear whether adiponectin and leptin are useful predictors of stroke in obese subjects; however, adiponectin and leptin might directly influence stroke incidence." (PMID 23431245, 2013). "Our study hypotheses were that there is a direct association between serum leptin levels and incident CVD (CHD and stroke) and an inverse association between serum adiponectin levels and incident CVD." (PMID 24350185, 2013). "Leptin was associated with stroke among men but not among women participants from the Northern Sweden study." (PMID 24350185, 2013). "A recently published review paper from 104 articles also did not give a clear conclusion whether adiponectin, leptin, and resistin levels or the single-nucleotide polymorphisms of their encoding genes are independently associated with stroke risk." (PMID 29225622, 2017). "Leptin may be more deeply related to decreasing of stroke as compared to adiponectin in SHRSP." (PMID 23876211, 2013). "On the other hand, there are controversial reports that adiponectin, but not leptin, levels are recognized as a predictor of the risk for stroke, or that leptin, but not adiponectin, levels are recognized as a predictor of the risk for stroke in men, but not women." (PMID 23431245, 2013). "Our study’s comprehensive findings advocate for the consideration of a combined therapy involving leptin-PEG-FBP and tissue plasminogen activator (tPA), pointing towards enhanced clinical effectiveness in stroke treatment." (PMID 38203830, 2024). "Triglyceride and leptin levels as well as IFN-β, IFN-γ and TNF-α were elevated with higher BMI values, and the IL-6 concentration was reduced with higher BMI values after stroke in our data." (PMID 37587512, 2023). "In patients with cardioembolic stroke, leptin levels were significantly higher than in remaining stroke cases (19.57 ± 20.53 ng/ml versus 13.17 ± 12.36 ng/ml, p < 0.05) and CHA2DS2-VASc score positively correlated with leptin levels only (p < 0.001)." (PMID 29225622, 2017). "This study reviewed and analyzed the results of thirteen studies investigating the effect of high leptin on the risks of developing CHD and stroke." (PMID 28278178, 2017). "Serum adiponectin, leptin, and resistin levels were determined by ELISA in 99 AIS patients and 59 stroke-free control group subjects." (PMID 29225622, 2017). "Though one of the best known functions of leptin is regulation of feeding behavior, leptin also plays essential roles in the regulation of cerebral blood flow and metabolism, cell differentiation, cognition and learning, and neurodegeneration, where it may play dual roles in stroke or epilepsy." (PMID 22530983, 2012). "Curiously, in ESRD, patients with a history of stroke presented higher leptin levels than those without stroke history, while patients with congestive heart failure showed lower leptin values that those without history of congestive heart failure." (PMID 36289903, 2022). "A significant inverse association was shown between leptin and coronary heart disease (CHD), with an overall OR of 1.16 (95% CI: 1.02–1.32), but not for stroke (OR = 1.21, 95% CI 0.98–1.48) under sociodemographic adjustment." (PMID 28278178, 2017). "Because of highest statistical differences in leptin levels in AIS patients, we first analyzed leptin levels in dependence on all main kinds of stroke etiology with the presence or absence of MetS." (PMID 29225622, 2017).